RNF5 (ring finger protein 5)
Diseases named in the same sentence as RNF5 in open-access papers (continued):
Sharing a sentence is not in itself a finding about the gene and the disease.
Parkinson disease (3 papers, 2008 to 2024). A progressive degenerative disorder of the central nervous system characterized by loss of dopamine producing neurons in the substantia nigra and the presence of Lewy bodies in the substantia nigra and locus coeruleus. "Interestingly, RNF5 has also been shown to be upregulated in brain (Substantia Nigra) from Parkinson Disease patients, therefore pointing to a possible broader role of this E3 ligase in degenerative disorders." (PMID 18270596, 2008).
primary effusion lymphoma (3 papers, 2023). A large B-cell lymphoma located in the body cavities, characterized by pleural, peritoneal, and pericardial fluid lymphomatous effusions and that is always associated with human herpes virus-8 (HHV-8). "Both RNF5 silencing and RNF5 loss dramatically suppressed xenograft tumor growth, suggesting that inhibition of RNF5 effectively suppressed tumor growth of primary effusion lymphoma." (PMID 36656913, 2023). "Recently, we revealed that RNF5 inhibition suppresses the lytic replication of Kaposi’s sarcoma-associated herpesvirus and the growth of primary effusion lymphoma by targeting EphA3 and EphA4, emphasizing the positive function of RNF5 in tumor virus replication and tumorigenesis." (PMID 37816703, 2023). "Thus, our study provides a promising candidate and approach for developing the treatment of KSHV-positive diseases and primary effusion lymphoma by selective RNF5 inhibition." (PMID 36656913, 2023). "Interestingly, in the study of Kaposi sarcoma-associated herpesvirus (KSHV) and its association with primary effusion lymphoma (PEL), a fascinating connection between RNF5 and Ephrin receptors has been discovered, opening up potential new avenues for the treatment of KSHV and management of PEL." (PMID 38250078, 2023). "Our study suggests that RNF5 plays the critical roles in KSHV lytic infection and tumorigenesis of primary effusion lymphoma." (PMID 36656913, 2023).
asthma (2 papers, 2022 to 2024). "The results from the Asian population replicated 16 associations (including BTNL2-asthma), and the Black population replicated 7 associations (including RNF5-celiac disease)." (PMID 39009607, 2024). "A recent study reported colocalizations between eQTLs for HLA-B, HLA-DQB1, HLA-DQA1, HLA-DRA, TAP1, and RNF5 in induced pluripotent stem cells with asthma GWAS SNPs." (PMID 35606880, 2022).
celiac disease (2 papers, 2024 to 2025). An autoimmune genetic disorder with an unknown pattern of inheritance that primarily affects the digestive tract. "We hypothesize that the downregulation of RNF5 in celiac disease may result in the loss of this protective effect, thereby increasing susceptibility to cataract." (PMID 40833330, 2025). "RNF5 was downregulated in both celiac disease and lens injury models and was identified as a significant protective factor for senile and other cataracts." (PMID 40833330, 2025). "For instance, CFB was observed to alleviate the risk associated with celiac disease (ORUKB: 0.46, ORFinGenn: 0.59) while RNF5 heightened the risk for celiac disease (ORUKB: 3.41, ORFinGenn: 3.74)." (PMID 39009607, 2024). "However, further studies are necessary to confirm the role of RNF5 in both diseases and to assess its expression in the lenses of patients with celiac disease." (PMID 40833330, 2025). "RNF5 was downregulated in celiac disease compared to controls." (PMID 40833330, 2025). "Currently, no studies have directly investigated the role of RNF5 in either celiac disease or cataract." (PMID 40833330, 2025).
colitis (2 papers, 2019 to 2021). Inflammation of the colon. "RNF5 was shown to restrict colitis in an S100A8-dependent manner, as RNF5 deficient mice demonstrated S100A8 accumulation that induced colitis, which was abrogated by S100A8-neutralizing antibodies." (PMID 34356615, 2021). "Noteworthy, Rnf5−/− mice exhibit basal intestinal inflammation, which develops into acute colitis following DSS administration." (PMID 30940817, 2019). "Moreover, RNF5-low/S100A8-high sections of the gut epithelium of colitis patients correlated with severe inflammation." (PMID 34356615, 2021).
inclusion body myositis (2 papers, 2008 to 2012). A slowly progressive degenerative inflammatory disorder of skeletal muscles characterized by late onset weakness of specific muscles and distinctive histopathological features. "Deregulated expression of RNF5 in the muscle of RNF5 transgenic mice results in the formation of inclusion body myositis, an endoplasmic reticulum (ER) stress-associated muscular disorder." (PMID 23093945, 2012).
leukemia (2 papers, 2021 to 2023). A malignant (clonal) hematologic disorder, involving hematopoietic stem cells and characterized by the presence of primitive or atypical myeloid or lymphoid cells in the bone marrow and the blood. "Collectively, these data show that RNF5 loss decreases the colony-forming capacity of MLL-AF9–transformed pre-leukemic cells in vitro and delays leukemia progression in vivo." (PMID 34518534, 2021). "Western blot analysis of splenocyte lysates revealed more abundant expression of the cell cycle regulatory protein p27 in shRNF5 relative to control cells, consistent with our in vitro data and with the delayed leukemia progression observed following RNF5 KD." (PMID 34518534, 2021). "Inhibition of RNF5 can suppress AML cell growth and improve the responsiveness to HDAC inhibitors, indicating that RNF5 could act as a candidate target for chemotherapy of leukemia and lymphoma." (PMID 36656913, 2023). "Next, we asked how RNF5 knockdown (RNF5-KD) would impact leukemia cell growth in vitro." (PMID 34518534, 2021). "Interestingly, animals injected with RNF5-KD cells exhibited a markedly decreased leukemia burden and prolonged survival relative to control mice." (PMID 34518534, 2021). "We next asked whether RNF5 activity modulates leukemia growth in vivo." (PMID 34518534, 2021). "Here we identify an important role for the ubiquitin ligase RNF5 in AML and demonstrate how RNF5 contributes to this form of leukemia." (PMID 34518534, 2021).
pancreatic cancer (2 papers, 2018 to 2023). "Depletion of stromal hedgehog signaling Smoothened promoted proliferation of pancreatic cancer via initiating RNF5-induced degradation of PTEN and subsequent activation of AKT." (PMID 36733484, 2023).
SARS-CoV infection (2 papers, 2023 to 2025). "For example, the E3 ligase RNF5-mediated degradation of envelope (E) protein curtails severe acute respiratory syndrome–coronavirus 2 (SARS–CoV-2) replication." (PMID 39655951, 2025).
acute lymphoblastic leukemia (1 paper, 2021). Leukemia with an acute onset, characterized by the presence of lymphoblasts in the bone marrow and the peripheral blood. "Analysis of RNA-seq datasets for various cancer cells in the Cancer Cell Line Encyclopedia (CCLE) database identified a higher copy number and levels of RNF5 transcripts in AML, chronic myeloid leukemia (CML), and T-cell acute lymphoblastic leukemia (T-ALL) relative to other tumor types." (PMID 34518534, 2021).
Autoimmunity (1 paper, 2016). The occurrence of an immune reaction against the organism's own cells or tissues. "Smoking was significantly associated with hypomethylation of a DMR overlapping the promoter region of the RNF5 and the AGPAT1, which are implicated in inflammation and autoimmunity, whereas DMARD treatment induced hypermethylation of the same region." (PMID 27909437, 2016). "Thus, both RNF5 and AGPAT1 have been associated with inflammation and autoimmunity." (PMID 27909437, 2016).
cataract (1 paper, 2025). Partial or complete opacity of the crystalline lens of one or both eyes that decreases visual acuity and eventually results in blindness. "Our findings indicate that RNF5 tends to be downregulated in lens injury models and functions as a protective factor against cataracts, suggesting its potential role in maintaining lens epithelial integrity." (PMID 40833330, 2025). "Furthermore, MR analysis indicated that RNF5 is a significant protective factor for both senile and other cataracts." (PMID 40833330, 2025).
chronic hepatitis B (1 paper, 2025). "RNF5, either alone or in combination with other antiviral agents such as CAMs, may hold promise for achieving a functional cure for chronic hepatitis B." (PMID 40236486, 2025).
COVID-19 (1 paper, 2023). A disease caused by infection with severe acute respiratory syndrome coronavirus 2. "Importantly, the mRNA level of RNF5 was consistently higher in mild COVID-19 than that found in patients with severe symptoms." (PMID 36737599, 2023). "We also found that RNF5 is distinctively expressed in different age groups and in patients displaying different disease severity, which may be exploited as a prognostic marker for COVID-19." (PMID 36737599, 2023).
Crohn disease (1 paper, 2016). A gastrointestinal disorder characterized by chronic inflammation involving all layers of the intestinal wall, noncaseating granulomas affecting the intestinal wall and regional lymph nodes, and transmural fibrosis. "RNF5 has been shown to be downregulated in patients with established Crohn’s disease and ulcerative colitis as well as in patients with spondyloarthritis and chronic gut inflammation." (PMID 27909437, 2016).
duodenitis (1 paper, 2024). Acute or chronic inflammation of the duodenum. "Others included 41 GWS genes for GERD (Pgene-GERD < 2.62 × 10−6), 11 for PUD (Pgene-PUD < 2.62 × 10−6), three (RNF5, HLA-DQA1, and HLA-DQB1) for gastritis-duodenitis (Pgene-gastritis-duodenitis < 2.62 × 10−6), and three (HLA-C, PITPNM2, and MPHOSPH9) for IBS (Pgene-IBS < 2.62 × 10−6)." (PMID 38802514, 2024).
gastric cancer (1 paper, 2025). A primary or metastatic malignant neoplasm involving the stomach. "Furthermore, acetylated ATG2B undergoes SIRT1-mediated deacetylation, which enhances its binding to RNF5, thereby promoting autophagy and tumor progression in gastric cancer." (PMID 40936702, 2025).
influenza (1 paper, 2023). An acute viral infection of the respiratory tract, occurring in isolated cases, in epidemics, or in pandemics; it is caused by serologically different strains of viruses (influenzaviruses) designated A, B, and C, has a 3-day incubation period, and usually lasts for 3 to 10 days. "The treatment of cells with miR-483-3p leads to the downregulation of RNF5 at both the gene and protein levels, enhancing the innate immune response against influenza." (PMID 38250078, 2023).
lymphoma (1 paper, 2023). A malignant (clonal) proliferation of B- lymphocytes or T- lymphocytes which involves the lymph nodes, bone marrow and/or extranodal sites. "After all lymphoma and invasive tumors in the abdominal cavity were collected and weighed, the total tumor weight was reduced in mice injected with RNF5 KO BCBL1 cells compared with mice injected with control cells." (PMID 36656913, 2023). "Thus we conclude that RNF5 inhibition might preferentially generate greater suppression in tumorigenesis of KSHV-positive PEL than KSHV-negative lymphoma." (PMID 36656913, 2023).
muscular dystrophy (1 paper, 2008). Muscular dystrophy (MD) refers to a group of more than 30 genetic diseases characterized by progressive weakness and degeneration of the skeletal muscles that control movement. "Unlike in sIBM, common muscular dystrophies associated with mutations in proteins of the dystrophin glycoprotein complex (DGC) such as Duchenne or Becker forms of muscular dystrophy, did not exhibit any alteration in the pattern or amount of RNF5 expression." (PMID 18270596, 2008).
Pendred syndrome (1 paper, 2022). Pendred syndrome (PDS) is a clinically variable genetic disorder characterized by bilateral sensorineural hearing loss and euthyroid goiter. "Retention of misfolded Pendrin mutants in the endoplasmic reticulum is considered the main pathological mechanism of Pendred syndrome, and RNF5 has significant effects on Pendrin protein degradation." (PMID 36270989, 2022).
retinal degeneration (1 paper, 2020). Degeneration of the retina. "Furthermore, ERAD of misfolded proteins via SORDD1 is likely conserved in mammals, as RNF5 and RNF185 also suppressed Rh1G69D-induced retinal degeneration." (PMID 33137101, 2020).
Sjögren’s syndrome (1 paper, 2016). "Although, we did not collect samples for quantification of mRNA in whole blood, our results accord with previously published gene expression studies on the RNF5 and the S100A6 in peripheral blood from RA patients and patients with Sjögren’s syndrome." (PMID 27909437, 2016).
type 1 diabetes (1 paper, 2016). "Increased expression of this gene has been reported in PBMCs from RA patients with active disease, and SNP genotypes of both RNF5 and AGPAT1 have been associated with susceptibility to type 1 diabetes." (PMID 27909437, 2016).
tumor (23 papers, 2011 to 2025). "Loss of RNF5 induces innate immunity, antitumor immunity, inflammation and autophagy, which are highly related to tumor suppression." (PMID 37816703, 2023). "Consequently, RNF5 silencing or RNF5 loss suppresses PEL-derived xenograft tumor growth, with increased EphA4 levels and decreased oncogenic KSHV viral gene expression and genomic viral DNA loads, providing a novel therapeutic candidate for KSHV lytic infection and KSHV-positive PEL treatment." (PMID 36656913, 2023). "Upon binding, inh‐2 stabilizes CFTR, preventing RNF5 from recognizing and ubiquitylating it, and has shown promising anti‐tumor activity in preclinical studies by inhibiting tumor growth and promoting apoptosis in various cancer models." (PMID 39021054, 2024). "Here, we demonstrated that RNF5 inhibition suppresses PEL xenograft tumor growth and oncogenic KSHV lytic replication through increased EphA3 and EphA4 levels and decreased downstream pathways." (PMID 36656913, 2023). "RNF185 is an RNF5 homolog, and RNF5 has been found to exert pro- or anti-tumor activity depending on the tumor model." (PMID 38139010, 2023). "To further investigate the mechanism of RNF5 inhibition in tumor suppression, we analyzed the global differential gene expression in these xenograft tumors by microarray analysis." (PMID 36656913, 2023). "In contrast, RNF5 inhibition results in enhanced autophagy and antitumor immunity, restricting bacterial infection and tumor growth." (PMID 36656913, 2023). "The tumor weights were similarly affected by transduction of EphA2 shRNA alone or RNF5 siRNA alone, and the double transduction abolished their effect and generated the approximately equal tumor weights compared with the control group." (PMID 37816703, 2023). "To further confirm the tumor-suppressive function of EphA2 induced by RNF5 inhibition, we established single or double RNF5- and/or EphA2-knockdown MCF7 cells and injected them into BALB/c nude mice to detect the xenograft tumor growth." (PMID 37816703, 2023). "The tumor growth was increased by EphA2 depletion while it was decreased by RNF5 depletion, and double depletion exhibited slightly slow growth compared with control tumor growth." (PMID 37816703, 2023). "RNF5 inhibition decreased PEL xenograft tumor growth and downregulated viral gene expression, cell cycle gene expression, and hedgehog signaling in xenograft tumors." (PMID 36656913, 2023). "As the expression levels of viral genes and the production of infectious viral particles are essential for viral persistence in KSHV-related neoplasms, we detected genomic viral DNA in tumors to address the influence of RNF5 KO on viral factors in vivo." (PMID 36656913, 2023). "Taken together, these data indicated that the RNF5 activator Analog-1 affected tumor cells through down modulation of glutamine availability and energy metabolism." (PMID 35406574, 2022). "In this connection, rnf5−/− mice presented alterations in the gut microbiota composition, which, in turn, contributed to increase the host antitumor immunity, limiting tumor progression." (PMID 35406574, 2022). "From these observations, it is evident that the role of RNF5 in cancer is still controversial and its pro- or anti-tumor activity likely depend on the tested tumor type." (PMID 35406574, 2022). "For example, the changes in gut microbiota exhibited by Rnf5–/– mice contribute to antitumor immunity and limit tumor expansion." (PMID 35992663, 2022). "The importance of the gut microbiota in the control of tumor growth in Rnf5−/− mice was confirmed by an antibiotic cocktail treatment that prevented tumor growth inhibition." (PMID 33800394, 2021).